S1PR1 (sphingosine-1-phosphate receptor 1)
Diseases named in the same sentence as S1PR1 in open-access papers (continued):
Sharing a sentence is not in itself a finding about the gene and the disease.
tumor (continued). "The expression of S1PR1 was significantly decreased in tumor tissues of BRCA, LUAD and LUSC." (PMID 32799825, 2020). "Strategies to enhance S1PR1 function in the tumor vasculature may enhance the cytotoxic killing effect and chemotherapy effect of targeted anti-cancer therapy." (PMID 32799825, 2020). "We examined whether S1PR1 overexpression could reverse the tumour suppressive effects of miR-363 on ccRCC cell proliferation, migration and invasion." (PMID 32536815, 2020). "The relationship between S1PR1 and tumor-infiltrated immune cells was analyzed using TIMER." (PMID 32799825, 2020). "Thus, targeted inhibition of the S1PR1/STAT3 can inhibit tumor proliferation and growth in a STAT3-dependent manner." (PMID 33101013, 2020). "Our results suggest that miR-363 acts as a tumour suppressor by directly targeting S1PR1 in ccRCC and may be a potential new therapeutic target for ccRCC." (PMID 32536815, 2020). "Besides, IHC results showed that CSO significantly reduced the expression level of S1PR1 in tumor tissue sections." (PMID 33101013, 2020). "Overall, these results suggest that miR-363 may serve as a tumour suppressor and that S1PR1 may act as an oncogene in ccRCC." (PMID 32536815, 2020). "On the contrary, low expression of S1PR1 could lead to reduced infiltrated effector cells in the tumor microenvironment." (PMID 32799825, 2020). "Indeed, most TIL subpopulations had attributes of tissue residency, including low S1pr1 and Klf2 expression and high Cd69 expression, contrasting with Arm and most tumor dLN clusters." (PMID 31801070, 2019). "S1PR1 overexpression resulted in a significant increase in tumor size compared with control tumors." (PMID 31534132, 2019). "Furthermore, pharmacological blockage of S1PR1 by FTY720 or scavenging extracellular S1P by an anti-S1P-neutralizing antibody inhibited tumor-induced angiogenesis." (PMID 31357710, 2019). "One study in MB49 tumor cells showed that the phosphorylation of C-terminal domain of S1PR1 could directly promoting consistent STAT3 activation." (PMID 31438989, 2019). "RNA interference experiments have shown that S1PR1 is required in vivo for tumor angiogenesis." (PMID 31807117, 2019). "Mechanistically, S1PR1 signaling in lymph vessel-associated macrophages induced NLRP3 expression and IL-1β production, which showed direct pro-lymphangiogenic activity, thereby accelerating tumor progression by promoting metastasis." (PMID 31379883, 2019). "To determine whether S1PR1 promoted tumor angiogenesis and decreased VM formation via RhoA signaling, we used a RhoA inhibitor to block the separation of VE-cadherin and β-catenin in the tube formation assays." (PMID 30814488, 2019). "HIF-1α expression under these conditions established a pro-angiogenic macrophage phenotype, indicating that S1P/S1PR1 signaling may promote tumor angiogenesis in general." (PMID 31379883, 2019). "However, because the therapeutic efficacy of suppression or gene knockout of S1PR1 or S1PR3 varies widely for different types of tumors (currently only in tumor models or cells), further preclinical and even clinical trials are necessary." (PMID 31807117, 2019). "S1PR1 promoted tumor endothelial-dependent vessel and decreased VM formation via RhoA signaling." (PMID 30814488, 2019). "The impact of S1PR1 on CRC cell metastasis was then investigated following xenotransplantation into nude mice through intrasplenic injection, and we found that the number of distant masses was significantly increased in S1PR1 overexpression tumor cells at 6 weeks post injection." (PMID 31534132, 2019). "Activation of S1PR1 has been reported to be engaged in the regulation of many malignant biological phenotypes of tumors, such as tumor growth, invasion, migration, angiogenesis, and radio-resistance, functioning as an important oncogenic regulator in many cancers." (PMID 31438989, 2019).
tumor (continued). "Studies report that S1PR1 induces persistent activation of STAT3, and STAT3, a transcription factor for S1PR1, induces S1PR1 expression in a positive feedback loop for maintaining persistent STAT3 activation in tumor cells and the tumor microenvironment for malignant progression." (PMID 30377291, 2018). "Our results support the notion that down‐regulation of S1PR1 may contribute to tumour formation in NKTL." (PMID 27239439, 2016). "Accumulating evidence shows that tumor-derived factors and tumor-cell-signaling mediators, such as Hsp72 and S1pr1, activate MDSCs to potentiate their immunosuppressive functions or increase the recruitment and colonization of these cells into pre-metastatic tissues." (PMID 24021059, 2013). "However, contrasting findings indicate that S1PR1 may also modulate tumor vascular normalization and maintain vascular permeability, thereby exerting inhibitory effects on tumor growth and metastasis." (PMID 39551792, 2024). "Moreover, STAT3 may promote tumor progression by modulating the immune response within tumor microenvironments through several signaling pathways, including S1PR1, JAK, and IL-6." (PMID 39738726, 2024). "However, S1PR1 on VECs also supports VEGFR2-mediated angiogenic signaling during tumor growth." (PMID 37142226, 2023). "However, in other tumor entities such as glioblastoma and other intracranial tumors, S1PR1 downregulation is an important tumor-mediated mechanism of T cell dysfunction by trapping T cells in the bone marrow and preventing their migration to the tumor site." (PMID 35163211, 2022). "According to these observations, a potential of S1PR1 as an immune-oncology drug target by reducing intratumoral accumulation of Tregs and pro-tumor cytokine secretion by macrophages resulting in reduced tumor growth and metastasis is prominently discussed in the literature." (PMID 35163211, 2022). "Augmented tumor development and metastasis associated with deficient vessel maturation was observed in mice lacking S1PR1 in endothelial cells, while overexpression of S1PR1 in endothelial cells normalized tumor vessels and improved the response to tumor therapy." (PMID 35163211, 2022). "Consequently, one might argue that it may be beneficial for cancer patients to target S1PR1 in order to prevent enhanced accumulation of pro-tumor Tregs or enhance Trm abundance within tumors." (PMID 35163211, 2022). "Thus, S1PR1 may exhibit tumor-suppressive attributes in the different cancers in the different histological subtypes or stage-specific manner." (PMID 34235182, 2021). "By using tumor ECs, EC-S1PR1−/- mice and S1PR1 antagonist, we showed that VEGF-VEGFR2 pathway requires EC-S1PR1-induced signaling to efficiently drive tumor vascularization and growth, indicating combining S1PR1 antagonist with anti-VEGF/VEGFR2 therapy may eradicate resistant tumors." (PMID 32944615, 2020). "In addition, the down-regulation of S1PR1 may have profound effects on vasculogenic mimicry in tumor microenvironment." (PMID 32799825, 2020). "However, in the case of S1PR1 null tumor ECs, VEGF resulted activation of the canonical pathway in which VEGF induced phosphorylation of VEGFR2 at Y1175 was followed by internalization with the co-operative endocytic machinery leading to activation of ERK1/2/3." (PMID 32944615, 2020). "Therefore, it is necessary to clarify the role of S1PR1 in tumor development and progression." (PMID 32799825, 2020). "Therefore, the question is whether we can decrease tumor viability and growth by inhibiting S1PR1 expression." (PMID 31807117, 2019). "However, the patients with high STAT3 tumor had a significantly higher risk of both disease progression (p = 0.009) and cancer-specific mortality (p = 0.009), but not with tumors expressing S1PR1 or IL-6." (PMID 30091994, 2018).
tumor (continued). "In addition, we identify, and confirm functionally, a novel mechanism by which Tregs target to and accumulate within a human tumor microenvironment, through the down regulation of S1PR1, SELL (L-selectin) and CCR7, potentially resulting in greater lymph node retention." (PMID 27228053, 2016). "While fingolimod inhibition of Tregs proliferation may abrogate the suppressive role of these cells in the tumor microenvironment, it has more recently been shown that S1PR1 signaling activates STAT3, resulting in accumulation of Tregs and tumor growth in an orthotopic model of breast cancer." (PMID 27800303, 2016). "We also observed that IL-7 increases S1PR1 transcription in human CD8+ T cells, which we have shown to be protective against tumor-induced T cell sequestration." (PMID 40244705, 2025). "The interaction between S1P and S1PR1 enhances lymphocyte migration to inflammatory sites, with ETO amplifying this response to inhibit tumor growth." (PMID 41476790, 2025). "To clarify the role of S1PR1 and FOXA1 in tumor growth, we established an in vivo subcutaneous xenograft model." (PMID 39551792, 2024). "In this study, two genes (AURKA and S1PR1) were screened as hub genes of OSU-2S treatment NSCLC by survival analysis and expression analysis, and the study has confirmed the tumour-growth-suppressive effect of OSU-2S in in vivo and in vitro experiments." (PMID 38794152, 2024). "S1P has five high affinity receptors, and it is generally believed that S1PR1 and S1PR3 promote tumor cell migration and survival." (PMID 38446289, 2024). "Next, to evaluate the role of secondary lymphoid organs in the differentiation of tumor-specific CD8+ T cells, we used FTY720 treatment to block sphingosine 1-phosphate receptor-1 and inhibit the migration of effector T cells from secondary lymphoid tissue." (PMID 38881188, 2024). "For example, FTY720, an S1P modulator that binds to S1PR1, S1PR3, S1PR4, and S1PR5, has been shown to inhibit tumor growth and aggressiveness in various cancer models." (PMID 37744269, 2023). "In a recent study, it was demonstrated that FTY720, by suppressing the S1PR1/STAT3 loop, inhibited tumor growth and desmoplasia and suppressed resistance to the chemotherapy drug gemcitabine." (PMID 36714534, 2023). "When the expression or activity of S1PR1 is inhibited, PDK1 expression is decreased and LATS1/1 is activated, leading to YAP inactivation and tumor cell senescence." (PMID 37828220, 2023). "These in vivo results suggested that ceramide in tumour tissue had an effect on the angiogenesis of HCC and that its level was regulated by EC S1PR1." (PMID 36068200, 2022). "Second, low and high expression of S1PR1 demonstrated opposing effects in in vitro and in vivo experiments, and the knockdown of S1PR1 expression was shown to decrease the density of HCC tumour-bearing mouse tumour vasculature." (PMID 36068200, 2022). "Data from a syngeneic tumor model with CD4+ T cell-specific ablation of S1PR1 indicate that S1PR1 on CD4+ T cells regulates intratumoral Treg expansion leading to CD8+ T cell suppression and tumor progression through STAT3-dependent activation of Tregs." (PMID 35163211, 2022). "Based on this, treatment with an antagonist of S1PR1, Siponomid, reduced angiogenesis and tumor growth in a DLBCL mouse model, indicating that S1P-S1PR1-mediated angiogenesis is a potential therapeutic target to subdue DLBCL." (PMID 36361536, 2022). "The pH-sensitive and tumor-targeted nanoparticle BAF312@cRGD-CaP-NP shows greatly improved antitumor efficacy and suppression of angiogenesis via the S1PR1/P-STAT3/VEGFA axis in BRCA, especially in TNBC." (PMID 34059068, 2021). "Apoptosis exosome vesicles (AEVs) are special exosomes overexpressing S1PR1 and S1PR3 released by the tumor cells in response to certain chemicals." (PMID 34283088, 2021).
tumor (continued). "As expected, the tumor and distant mucosa TRM populations showed high expression of Itgae (CD103) and low expression of S1PR1, confirming their tendency to reside within the tissue." (PMID 33979626, 2021). "Western blotting confirmed that S1PR1 is highly expressed in SK-HEP-1 solid tumors, while the expression of S1PR1 in muscle tissues from nude mice in the experimental group and MCF-7 tumor tissues is very low." (PMID 34484174, 2021). "Immunohistochemistry staining confirmed that a small amount of S1PR1 was expressed in vascular endothelial cells in lung, liver, spleen, kidney, muscle and MCF-7 tumor tissues, while the cell membranes of SK-HEP-1 tumors highly expressed S1PR1." (PMID 34484174, 2021). "Mechanistically, S1P activates S1PR1 amplifies VEGFR2‐dependent c‐Abl1 and Rac activation and EC migration to support tumor growth." (PMID 35201458, 2021). "Presence of S1PR1 leads to VEGFR2 phosphorylation at Y951, which retains VEGFR2 at the EC surface and promotes migration and tumor growth via sustained Rac1 activity." (PMID 34690821, 2021). "Studies have shown that STAT3 is a transcription factor for the S1PR1 gene, and enhanced expression of S1PR1 can continuously activate STAT3 and upregulate the expression of the IL-6 gene, thereby accelerating tumor growth and metastasis." (PMID 33101013, 2020). "MDSCs in the pre‐metastatic microenvironment can promote further amplification through the S1PR1‐STATS signalling pathway and help tumour cells penetrate into the circulatory system." (PMID 31957271, 2020). "S1PR1 is a G protein‐coupled receptor of lysophosphatidyl 1‐sphingosine, and its expression is increased in STAT3+ tumour cells." (PMID 31957271, 2020). "FTY720 reduces tumor growth, metastasis, angiogenesis, and enhances drug-sensitivity of TNBC as an antagonist of S1PR1." (PMID 33101013, 2020). "An increase in S1PR1 in CD4+ T-cells promotes STAT3 activation and JAK/STAT3-dependent Treg tumor migration, whereas STAT3 ablation in T-cells diminishes tumor-associated Treg accumulation and tumor growth." (PMID 31480382, 2019). "For instance, FTY720, an S1P agonist that binds to S1PR1, S1PR3, S1PR4, and S1PR5, has been indicated to suppress the growth and aggressiveness of tumor in several cancer models." (PMID 31807117, 2019). "Immunohistochemistry was conducted to identify protein expression of S1PR1 and p- STAT3 in tumor tissues." (PMID 31438989, 2019). "Western blot assay was used to evaluate S1PR1 and p-STAT3 expression in MDSCs after separation from the liver and tumor by magnetic antibody." (PMID 31534132, 2019). "S1PR1 has key functions in tumor metastasis and angiogenesis, and maintains persistent STAT3 activation by regulating both tumor cells and tumor-infiltrating myeloid cells." (PMID 30377291, 2018). "Moreover, S1PR1 was shown to be closely associated with persistent activation of signal transducer and activator of transcription-3 (STAT3) and IL-6 expression in both tumor cells and the tumor microenvironment, both of which contributed to tumor malignant progression and distant dissemination." (PMID 30242145, 2018). "The balance of the effect of S1P on S1PR1 and S1PR3 in the activity of MDSC in tumor niche requires further studies." (PMID 29467963, 2018). "Other relevant transcripts that were significantly induced in the tumor CD45+ cells include Bhlhe40, Eomes S1PR1, TIM3 and CX3CR1." (PMID 29423108, 2018). "Enhanced S1PR1 upregulated the expression of IL-6, a pro-inflammatory cytokine crucial for STAT3 activation, inflammatory cell-mediated transformation, and tumor progression." (PMID 27129720, 2016). "S1PR1 is differentially expressed on CLL cells and is reduced when cells are in a tumour supportive microenvironment compared to when cells are free in circulation." (PMID 26988915, 2016). "We first observed that S1PR1 could translocate from LEC cell surface to endoplasmic reticulum under the stimulation of LMW-HA, thus triggering tumor lymphangiogenesis." (PMID 39991586, 2025).
tumor (continued). "We have shown that tumor-derived S1P is a major chemoattractant for monocytes and macrophages, both in vitro and in animal models of DLBCL, an effect mediated by the S1P receptor S1PR1." (PMID 38339325, 2024). "S1PR1 and STAT3 stimulate and activate each other to synergistically enhance tumor growth." (PMID 36714534, 2023). "Immunohistochemistry showed that S1PR1 and p-histone H3 (marker of proliferation) protein levels were significantly decreased, whereas LATS1, LATS2, P62, and cleaved caspase-3 protein levels were significantly increased in S1PR1 knockout tumor tissue." (PMID 37828220, 2023). "Tumor vessels lacking S1pR1 exhibit excessive vascular sprouting and blunted barrier function, whereas overexpressing S1pR1 reduces vessel branching and tortuosity." (PMID 37781737, 2023). "Moreover, the analysis of the LGG cohort demonstrated a similar profile to S1PR1, S1PR2, S1PR3, and S1PR4, which are upregulated in tumor tissue, significantly so for S1PR2 and S1PR3." (PMID 37760448, 2023). "However, we also found that S1PR1 was selectively highly expressed on the vascular cells (CD31+ cells) of HCC tissues and was negatively or weakly expressed on other stromal tumour cells." (PMID 36068200, 2022). "Nevertheless, blocking S1PR1 could also prevent infiltration of T cells such as CD8+ cytotoxic T cells into tumors, which are needed to effectively kill tumor cells." (PMID 35163211, 2022). "We evaluated S1PR1 expression in normal or tumor tissues from four clinical cases and analyzed the epithelial–mesenchymal transition (EMT) marker together, which is thought to be regulated by S1PR1 expression, but with different effects in different tissues or spatial and temporal contexts." (PMID 34503284, 2021). "Fingolimod, an agonist of four S1PRs (including S1PR1, S1PR3, S1PR4, and S1PR5), induces receptor internalization and exerts antagonistic effects, which could markedly reduce the tumor load and abrogate the NF-κB/IL-6/STAT3/S1PR1 cascade." (PMID 34831211, 2021). "Targeting SPHK‐S1P‐S1PR signaling, including SP1, SPHK1, SPHK2, S1PR1, and S1PR2 by the use of specific inhibitors, represents an innovative strategy for anticancer therapy that has shown efficacy in in vitro studies and in tumor xenograft models." (PMID 34766135, 2021). "In vitro and in vivo studies both confirm that BAF312@cRGD-CaP-NPs showed dramatically improved tumor targeting ability and can effectively improve the antitumor effect of BAF312 and inhibit tumor angiogenesis, which is mediated through the S1PR1/P-STAT3/VEGFA pathway." (PMID 34059068, 2021). "In addition, S1PR1 signaling in T cells drives Treg accumulation in tumors, limits CD8+ T cell recruitment and activation, and promotes tumor growth." (PMID 34737957, 2021). "In addition, one of the main functions of the activation of the S1PR1 signaling pathway is the continuous activation of STAT3 in the form of phosphorylation, leading to overexpression of NF-κB and IL-6, which promotes tumor development." (PMID 33101013, 2020). "To validate this hypothesis in an in vivo tumor model, we quantified pAKT in S1PR2+/+ and S1PR1−/− tumor-bearing mice." (PMID 33225975, 2020). "The subsequent investigation of S1PR1 revealed that it might also be a prognostic gene in LUAD (in TCGA cohort and GSE72094), with interactions with some well-known tumor genes such as AKT1, STAT3 and CXCR4." (PMID 33628734, 2020). "The upregulation of the S1pr1 gene can activate STAT3 and promote tumour growth and metastasis." (PMID 31957271, 2020). "Enhanced S1PR1 expression activates STAT3 and upregulates IL-6 expression, a proinflammatory cytokine crucial for STAT3 activation and inflammatory cell-mediated transformation and tumor progression." (PMID 31534132, 2019). "Interestingly, in contrast to S1PR1, S1PR2 was reported to limit tumor development and angiogenesis in one study, which involved S1PR2 on myeloid cells." (PMID 31379883, 2019).